PPP2R5D (protein phosphatase 2 regulatory subunit B'delta)
Description:
The B regulatory subunit might modulate substrate selectivity and catalytic activity, and might also direct the localization of the catalytic enzyme to a particular subcellular compartment.
Synonyms: B56D; B56delta; HJS1; MRD35
Tractability: PROTAC: ubiquitination databases record sites on it; its protein half-life has been measured.
Gene: Protein-coding gene on chromosome 6 (42,984,538 to 43,012,346, forward strand). Ensembl gene ENSG00000112640.
Subcellular location: Cytoplasm; Nucleus
Subcellular location (Human Protein Atlas): Cytosol; Nucleoplasm
Pathways (Reactome):
Signal Transduction: Beta-catenin phosphorylation cascade; DARPP-32 events; Degradation of beta-catenin by the destruction complex; Disassembly of the destruction complex and recruitment of AXIN to the membrane; ERK/MAPK targets; ERKs are inactivated; Negative regulation of MAPK pathway; PI5P, PP2A and IER3 Regulate PI3K/AKT Signaling; RAF activation; RHO GTPases Activate Formins
Disease: APC truncation mutants have impaired AXIN binding; AXIN missense mutants destabilize the destruction complex; CTNNB1 S33 mutants aren't phosphorylated; CTNNB1 S37 mutants aren't phosphorylated; CTNNB1 S45 mutants aren't phosphorylated; CTNNB1 T41 mutants aren't phosphorylated; Signaling by GSK3beta mutants; Truncations of AMER1 destabilize the destruction complex
Cell Cycle: Amplification of signal from unattached kinetochores via a MAD2 inhibitory signal; EML4 and NUDC in mitotic spindle formation; Mitotic Prometaphase; Resolution of Sister Chromatid Cohesion; Separation of Sister Chromatids
Immune System: Co-inhibition by CTLA4; Co-stimulation by CD28
Metabolism: PP2A-mediated dephosphorylation of key metabolic factors; Regulation of glycolysis by fructose 2,6-bisphosphate metabolism
Hemostasis: Platelet sensitization by LDL
Gene Ontology:
Molecular function: protein binding; protein phosphatase regulator activity; protein phosphatase activator activity
Biological process: nervous system development; signal transduction
Cellular component: cytosol; nucleoplasm; protein phosphatase type 2A complex; nucleus; cytoplasm
Genetic constraint (gnomAD): Loss-of-function variants: 12 observed, 83.25 expected, observed/expected ratio (o/e) 0.14, 90% interval 0.091 to 0.23. The upper end of that interval is the gene's LOEUF score, 0.23, which puts it in group 1 of 6, group 1 being the genes least tolerant of losing a copy. Missense variants: 419 observed, 799.66 expected, observed/expected ratio (o/e) 0.52, 90% interval 0.48 to 0.57. Synonymous variants: 277 observed, 303.44 expected, observed/expected ratio (o/e) 0.91, 90% interval 0.83 to 1.01.
Gene-disease validity (ClinGen):
ClinGen rates the evidence that PPP2R5D causes each of these diseases.
complex neurodevelopmental disorder (autosomal dominant): Definitive. A disorder that involves more than one phenotype associated with the central nervous system, including but not limited to intellectual disability, autism, and seizures (epilepsy).
Homologues: Orthologues: chimpanzee PPP2R5D (100% identical), macaque PPP2R5D (99% identical), dog PPP2R5D (99% identical), rat Ppp2r5d (98% identical), pig PPP2R5D (97% identical), guinea pig PPP2R5D (97% identical), mouse Ppp2r5d (96% identical), rabbit PPP2R5D (90% identical), zebrafish ppp2r5d (86% identical), Drosophila melanogaster wrd (64% identical), Caenorhabditis elegans pptr-2 (61% identical), Caenorhabditis elegans pptr-1 (49% identical). Paralogues in human: PPP2R5C (74% identical), PPP2R5E (52% identical), PPP2R5A (51% identical), PPP2R5B (51% identical).
Diseases named in the same sentence as PPP2R5D in open-access papers:
PPP2R5D is named in the same sentence as 52 diseases in open-access papers, as found by Europe PMC text mining. Sharing a sentence is not in itself a finding about the gene and the disease. The quoted sentences say what the papers report.
Intellectual disability (15 papers, 2015 to 2025). "Clinically, pathogenic variants in PPP2R1A (encoding PP2A-A) and PPP2R5D (encoding PP2A-B) have been linked to NDDs characterized by severe intellectual disability, speech impairment, epilepsy, and developmental delay." (PMID 40839403, 2025). "Because mutations in multiple subunits, including PPP2R1A, PPP2R5B, PPP2R5C, and PPP2R5D, have been linked to intellectual disability, future studies will investigate their roles in eCB signaling and related neuropsychiatric disorders." (PMID 40839403, 2025). "Previously, de novo mutations in PPP2CA and another PP2A subunit, PPP2R5D, have been identified in patients with intellectual disability and developmental delay." (PMID 38450154, 2024). "Intriguingly, the PPP2R5D gene has recently been associated with intellectual disability and autism in human." (PMID 32609087, 2020). "Mutations that resulted in changes in the amino acid code and replacement of highly conserved amino acids in the PPP2R5D protein have been found to be strongly associated with neurodevelopmental delay and intellectual disabilities." (PMID 32074998, 2020). "Protein Phosphatase 2 Regulatory Subunit B′ Delta (PPP2R5D)-related intellectual disability (ID) and neurodevelopmental delay is a disorder that mainly occurs due to de novo mutations in the PPP2R5D gene." (PMID 32074998, 2020). "Protein phosphatase 2A is one of the four major Ser/Thr phosphatases, and disruptive mutations in the regulatory subunit PPP2R5d were found causative in prenatal overgrowth and intellectual disability." (PMID 30333727, 2018). "Clinical studies have linked heterozygous loss-of-function mutations in PP2A subunits, including PPP2R1A and PPP2R5D, to intellectual disability, though the underlying mechanisms remain unclear." (PMID 40839403, 2025). "Heterozygous missense variants in PPP2R5D cause Houge-Janssens syndrome 1, a rare NDD characterized by macrocephaly, developmental delay, intellectual disability, seizures, autism spectrum disorder, and early-onset Parkinson disease." (PMID 40340253, 2025). "The clinical signs of PPP2R5D-related disorder include moderate to severe intellectual disability, autism spectrum disorder, and neurodevelopmental delay immediately after birth." (PMID 32074998, 2020). "Protein Phosphatase 2 Regulatory Subunit B′ Delta (PPP2R5D)-related intellectual disability (ID) and neurodevelopmental delay results from germline de novo mutations in the PPP2R5D gene." (PMID 32074998, 2020). "We have identified heterozygous missense mutations in PP2A regulatory subunit B family genes PPP2R5B, PPP2R5C and PPP2R5D in individuals with overgrowth and intellectual disability." (PMID 25972378, 2015). "PPP2R5D-related NDD is characterized by moderate to severe developmental delay and intellectual disability, autism spectrum disorder, attention deficits, seizures, and speech and motor impairments." (PMID 40340253, 2025). "There has been a report of concomitant diagnosis of FXS with three other genetic conditions such as Duchenne muscular dystrophy (DMD), PPP2R5D-related and MYT1L-related intellectual disability." (PMID 38025430, 2023). "PPP2R5D is an interesting finding because its mutations can promote intellectual disability and the development of spatially restricted tauopathy by deregulating CDK5 and GSK3-beta in mice lacking PPP2R5D subunits." (PMID 35110995, 2021). "Other challenges include incorrect diagnosis by professionals as a result of the fact that the PPP2R5D-related neurodevelopmental and intellectual disability has a nonspecific phenotype and can present as different diseases (or solely as autism spectrum disorders)." (PMID 32074998, 2020).
developmental delay (6 papers, 2020 to 2025). "There is currently no cure for ID associated with PPP2R5D mutations, but symptoms can be managed, and the treatment of manifestations is the standard treatment for visual impairments, seizures, and developmental delays." (PMID 32074998, 2020). "In this review, we report the current understanding of the structure and functions of the PP2A–PPP2R5D holoenzyme, the pathogenic mutations in PPP2R5D, and the associated clinical signs of ID and developmental delay." (PMID 32074998, 2020). "Another child with gene duplication including part of PPP2R5D has been reported with signs of developmental delay." (PMID 32074998, 2020). "Different neuronal cell types are currently being derived by our team and others from induced pluripotent stem cells (iPSC) generated from individuals diagnosed with PPP2R5D-related developmental delay and ID." (PMID 32074998, 2020). "The PPP2R5D (Protein Phosphatase 2 Regulatory Subunit B’ Delta)-related disorder, also known as Houge–Janssens syndrome 1 (OMIM #616355) or Jordan’s syndrome, is an autosomal, dominant (AD) condition with onset in early childhood characterized by moderate-to-severe developmental delays." (PMID 39728742, 2024).
autism (5 papers, 2020 to 2023). Persistent deficits in social interaction and communication and interaction as well as a markedly restricted repertoire of activity and interest as well as repetitive patterns of behavior. "Further, our cell-based data is consistent with the recent addition of PPP2R5D to the list of autism susceptibility genes related to AKT3, PIK3CA, PTEN, TSC1/2, and mTOR." (PMID 33482199, 2021). "PPP2R5D is a known syndromic cause of ASD and rare de novo loss-of-function variant associated with autism." (PMID 34341515, 2021). "PPP2R5D plays a major role in negative regulation of the PI3K/AKT signaling pathway, autism or other brain related disorders." (PMID 35836293, 2022).
epilepsy (4 papers, 2020 to 2025). A brain disorder characterized by episodes of abnormally increased neuronal discharge resulting in transient episodes of sensory or motor neurological dysfunction, or psychic dysfunction. "Mechanistic studies done on hippocampal neuronal cultures showed that the epilepsy-causing mutation in the CACNB4 protein resulted in its inability to bind to PPP2R5D and thus prevented translocation of the CACNB4–PP2A–PPP2R5D complex to the nucleus." (PMID 32074998, 2020).
Hypoglycemia (4 papers, 2022 to 2025). A decreased concentration of glucose in the blood. "Under hypoglycemia/metformin treatment, upregulated Ppp2r5d dephosphorylates GSK-3β, leading to a decline in MCL-1 and cell death." (PMID 39200351, 2024).
Macrocephaly (4 papers, 2021 to 2025). Occipitofrontal (head) circumference greater than 97th centile compared to appropriate, age matched, sex-matched normal standards. "A common feature of individuals with PPP2R5D-related NDD is macrocephaly." (PMID 40340253, 2025).
Parkinson disease (4 papers, 2020 to 2025). A progressive degenerative disorder of the central nervous system characterized by loss of dopamine producing neurons in the substantia nigra and the presence of Lewy bodies in the substantia nigra and locus coeruleus. "Recently, the recurrent pathogenic PPP2R5D variants E198K and E200K have been associated with early-onset parkinsonism." (PMID 40340253, 2025). "For instance, missense pathogenic variants in the PP2A regulatory subunit PPP2R5D causing the NDD Houge-Janssens Syndrome 1 (MIM: 616355) have recently been associated with early-onset Parkinsonism." (PMID 39565297, 2025). "Here, we focus on developing a human model for PPP2R5D-related NDD, called Jordan syndrome, which has been linked to Early-Onset Parkinson’s Disease (EOPD)." (PMID 39460716, 2025). "The severity of PPP2R5D-mutation-related ID along with the association of PP2A dysfunction with Alzheimer’s disease, Parkinson’s-like symptoms, and cancer has generated a strong need to study the effects of these mutations on the development and functions of different neural cells." (PMID 32074998, 2020).
cardiac hypertrophy (3 papers, 2018 to 2024). "In addition, ISO led to an increase in mRNA level of classical-cardiac-hypertrophy- and stress-related genes in the left ventricle, particularly under Ppp2r5d-knockdown conditions, including atrial natriuretic peptide (Nppa), brain natriuretic peptide (Nppb), and myosin heavy chain (Myh7)." (PMID 39200351, 2024).
hepatocellular carcinoma (3 papers, 2022 to 2025). A malignant tumor that arises from hepatocytes. "We have demonstrated that cellular PPP2R5D protein was required for HCV infection in hepatoma cells." (PMID 35836293, 2022). "PPP2R5D interactes with HCV NS5B and is required for HCV infection in cultured hepatoma cells through facilitating HCV replication." (PMID 35836293, 2022).
autism spectrum disorder (2 papers, 2020 to 2025). A spectrum of developmental disorders that includes autism, and Asperger syndrome. "Mutations in PPP2R5D are associated with neurodevelopmental delay, autism spectrum disorder (ASD), ID, behavioral challenges, and so forth, which are seen soon after birth." (PMID 32074998, 2020).
Duchenne muscular dystrophy (2 papers, 2021 to 2023). Duchenne muscular dystrophy (DMD) is a neuromuscular disease characterized by rapidly progressive muscle weakness and wasting due to degeneration of skeletal, smooth and cardiac muscle. "Here, we describe three independent cases of FXS co-segregation with three different genetic conditions, consisting of Duchenne muscular dystrophy (DMD), PPP2R5D--related neurodevelopmental disorder, and 2p25.3 deletion." (PMID 34946857, 2021).
Neurodevelopmental delay (2 papers, 2020 to 2021). "Phenotype ontology analysis of our data sets identified top genes associated with neurodevelopmental delay, with phenotypic overlap in neurobehavior observed in individuals with PPP2R5D pathogenic variants." (PMID 33482199, 2021).
schizophrenia (2 papers, 2014 to 2017). A major psychotic disorder characterized by abnormalities in the perception or expression of reality. "PPP2R5D is in co-expression network in Wnt pathway of schizophrenia tissue sample." (PMID 25522158, 2014).
colorectal cancer (1 paper, 2016). A primary or metastatic malignant neoplasm that affects the colon or rectum. "Increase in expression of PHPT1, PPP2R5D, and two TRIB3 transcripts indicates that tumor-associated changes in alternative splicing can affect glucose metabolism in colorectal cancer." (PMID 28105922, 2016). "We first showed up-regulation of PHPT1 and PPP2R5D alternative transcripts in colorectal cancer." (PMID 28105922, 2016).
colorectal tumors (1 paper, 2016). "These eight isoforms encoded by OGDH, COL6A3, ICAM1, PHPT1, PPP2R5D, SLC29A1, and TRIB3 genes were up-regulated in colorectal tumors, and this is in concordance with the bioinformatics data." (PMID 28105922, 2016).
fragile X syndrome (1 paper, 2021). A genetic syndrome caused by mutations in the FMR1 gene which is responsible for the expression of the fragile X mental retardation 1 protein. "As the diagnosis of fragile X syndrome could not explain all the clinical findings of the proband, a trio WES was undertaken and revealed the presence in the proband of a de novo heterozygous variant c.592G>A p.(Glu198Lys) in the PPP2R5D gene (NM_006245.3)." (PMID 34946857, 2021).
heart failure (1 paper, 2024). Inability of the heart to pump blood at an adequate rate to meet tissue metabolic requirements. "In vivo knockdown of Ppp2r5d in an isoproterenol (ISO)-induced DCM mouse model aggravated the pathogenesis and ultimately led to heart failure." (PMID 39200351, 2024).
Insulin resistance (1 paper, 2020). Increased resistance towards insulin, that is, diminished effectiveness of insulin in reducing blood glucose levels. "The specific mechanism utilized by SNRK to prevent insulin resistance in adipose tissue is through protein phosphatase 2 regulatory subunit B’ delta (PPP2R5D) phosphorylation, which impacts PP2A activity and phosphorylation of AKT." (PMID 32968716, 2020).
ischemic cardiomyopathy (1 paper, 2024). Ischemic cardiomyopathy is a cardiomyopathy in which a weakness in the muscle of the heart due to inadequate oxygen delivery to the myocardium with coronary artery disease being the most common cause. "Our previous study identified an altered mRNA level of protein phosphatase 2 regulatory subunit B’ delta (Ppp2r5d) in the plasma of DCM patients as compared to that of ischemic cardiomyopathy (ICM) patients and healthy individuals (GEO: GSE138678)." (PMID 39200351, 2024).
Myocardial fibrosis (1 paper, 2024). "During DCM development, downregulation of Ppp2r5d promotes mitochondrial dysfunction and apoptosis in cardiomyocytes as well as aggravating myocardial fibrosis and ventricular remodeling." (PMID 39200351, 2024).
Stroke (1 paper, 2016). Sudden impairment of blood flow to a part of the brain due to occlusion or rupture of an artery to the brain. "Grb2, Acot11, Acat2, Scp2, Anp32b and Ppp2r5d were down-regulated after stroke." (PMID 27699085, 2016).
virus infection (1 paper, 2022). "PPP2R5D was first identified in NS5B pull-down assay and further studied its role in HCV infection through PPP2R5D knockout, complementation, virus infection, and replicon analysis." (PMID 35836293, 2022).